HGF (hepatocyte growth factor)
Diseases named in the same sentence as HGF in open-access papers (continued):
Sharing a sentence is not in itself a finding about the gene and the disease.
bladder cancer (continued). "IL-1α in bladder cancer cell CM induces the release of IL-8, HGF, MMP-2, GM-CSF and monocyte chemotactic protein (MCP)-1 by CAFs, which, in turn, reciprocally induce migration and invasion in the tumor cells through MCP and HGF." (PMID 37046676, 2023). "To further understand the role of EMT in bladder cancer we utilised an in vitro-based model, which can undergo EMT in short-term cultures and compared real-time changes in cell plasticity with transcriptomics following HGF treatment." (PMID 31554791, 2019). "In summary, MEK/ERK 1/2 signaling is involved in the transactivation of Axl and PDGFR-α by HGF/c-Met pathway in human bladder cancer cell lines, but is independent of ras or Src activity." (PMID 21496277, 2011). "For instance, miR-199a-5p is known to inhibits VEGF-induced tumorigenesis and suppresses human bladder cancer cell metastasis by targeting C-C chemokine receptor type 7 (CCR7); this miRNA is also documented to target ETS-1 and suppresses HMEC angiogenesis by inhibiting VEGF and HGF signaling." (PMID 31188886, 2019).
ischemia (28 papers, 2011 to 2025). A hypoperfusion of the BLOOD through an organ or tissue caused by a PATHOLOGIC CONSTRICTION or obstruction of its BLOOD VESSELS, or an absence of BLOOD CIRCULATION. "HGF has been confirmed closely relating to liver repair after injury by various causes (chemical poison, infection, ischemia, physical injury or PHx, etc.)." (PMID 35370682, 2022). "BINCs have been shown to exhibit high expression levels of neuroprotective factors, such as IGF-1 and the hepatocyte growth factor (HGF), and to prevent the exacerbation of the tissue damage caused by injury and ischemia." (PMID 32967118, 2020). "Interestingly, MSC induced a rise in HGF levels also in another rat model of renal diseases, i.e. anti-Thy 1 nephritis and ischemia-reperfusion injury and in both models HGF overexpression was associated with prevention of renal damage." (PMID 25277788, 2014). "They transplanted HGF-overexpressing DPSCs into the brains of rats following transient middle cerebral artery occlusion to determine whether the transplanted cells could attenuate brain damage associated with post-ischemia/reperfusion injury." (PMID 41283323, 2025). "Dual therapy based on the combination of VEGF and HGF as a pro-angiogenesis therapy has been investigated as a treatment for different conditions characterized by ischemia." (PMID 40822341, 2025). "In the context of ischemic stroke, HGF mitigates the decline in tight junction protein levels and diminishes Blood–Brain Barrier disruption, thereby ameliorating cerebral edema following ischemia." (PMID 39170073, 2024). "After analysis of ischemia-induced injury parameters, we studied possible angio- and neurogenic processes that can be induced by HGF/VEGF plasmid injection as both used growth factors are known to have angio- and neurogenic potency widely implied in GT." (PMID 36497083, 2022). "Previous studies revealed that HGF can inhibit neutrophil infiltration via the downregulation of Selectin-E on the endothelial cell surface, which suppresses ischemia-related injury in various organs." (PMID 32680554, 2020). "We thought that immediately after thawing, the cell sheet is in a state similar to ischemia and malnutrition, and that transcription of HGF, VEGF, SDF1 was promoted." (PMID 30200961, 2018). "HGF which usually mediates antifibrotic effects and acts as a mobilizing factor on the contrary showed a downregulation in WJ-MSCs under ischemia." (PMID 28265289, 2017). "We sought to determine whether DPSCs that overexpress HGF can enhance their therapeutic effects on brain damage post-ischemia/reperfusion injury." (PMID 30151417, 2018). "Hepatocyte growth factor (HGF) has neuroprotective effects against ischemia-induced injuries." (PMID 30151417, 2018). "Thus, depletion of HGF attenuated the inhibitory actions of SHED-CM on apoptosis in response to ischemia." (PMID 26542315, 2015). "Indeed, HGF is able to attenuate the increase in NADPH oxidase activity observed in hippocampus cells after ischemia." (PMID 23301029, 2013). "This hypothesis is further supported by a recent study by Ellison and coworkers, where intra-coronary delivery of IGF-1/HGF significantly increased c-Kit+/Nkx2.5+ cardiac progenitor cells in the infarct and border regions in a pig ischemia model." (PMID 22590612, 2012). "Although VEGF and HGF have several points of interconnection throughout their downstream signaling and even through receptor regulation, their mechanism of action for controlling EC permeability and proliferation can differ, leading to different outcomes in improving ischemia recovery." (PMID 40822341, 2025). "In the presence of ischemia, the expression of VEGF, stromal cell-derived factor 1 (SDF-1), hepatocyte growth factor (HGF), and endothelin 1 (ET-1) is increased, thereby stimulating the recruitment of EPCs to the ischemic sites." (PMID 37899988, 2023).
ischemia (continued). "Similarly, hypoxic preconditioning of human MSCs resulted in increased expression of cMET, the receptor for scatter factor/hepatocyte growth factor (HGF), increased cell motility, and improved hindlimb ischemia recovery." (PMID 35054878, 2022). "In conclusion, ischemia-reperfusion injury is the strongest stimulus for activation of endogenous cardiomyocyte regeneration, correlating to the endogenous up-regulation of IGF-1 and HGF." (PMID 22590612, 2012). "In conclusion, ischemia-reperfusion injury was the strongest stimulus with both global and focal cardiomyocyte progenitor cell marker up-regulations, correlating to the endogenous up-regulation of the growth factors IGF-1 and HGF." (PMID 22590612, 2012). "The HGF levels did not correlate with ischemia time, age, or creatinine levels at admission." (PMID 41282338, 2025). "Thus, in addition to HGF, VEGF, and possibly other growth factors, Ang-1 represents another critical component of the microenvironmental response that drives both vascular- and muscle-specific responses to ischemia." (PMID 26042050, 2015). "Intriguingly, hosts exhibited a spontaneous upregulation of VEGF, bFGF, HGF and SDF-1α on day 3 and day 7 when compared to day 0 (P<0.05 within control group, respectively), indicating some degree of endogenous angiogenic factors mobilization in response to hindlimb ischemia." (PMID 23029141, 2012).
renal cell carcinoma (28 papers, 2014 to 2025). "However, the incidence and growth of tumours from xenografts of renal cell carcinoma cells were increased and associated with higher hepatocyte growth factor (HGF) expression in the tumour cells." (PMID 32397238, 2020). "This review focuses on the cell-surface pro-HGF activation system in urological cancers, including prostate cancer (PC), renal cell carcinoma (RCC), and urothelial carcinoma (UC) of bladder, and summarizes its significance in the progression of cancer." (PMID 32290402, 2020). "In this study, we employed a mouse model of renal cell carcinoma (RCC) bone metastasis to clarify the significance of the HGF/MET signaling axis and the regulator of HGF activator inhibitor type-2 (HAI-2)." (PMID 29890660, 2018). "c-Met and its only known ligand, hepatocyte growth factor (HGF), have been implicated in tumor development, invasion, migration and angiogenesis in solid tumor malignancies, including renal cell carcinoma (RCC)." (PMID 29262573, 2017). "In renal cell carcinoma, NR2C2 could promote renal cell carcinoma metastasis via HGF/Met and miR490-3p/vimentin signals." (PMID 34956884, 2021). "In addition, we further confirmed IRCR201-triggered agonistic effect by investigating the HGF/c-Met signaling pathway in Caki1 renal cell carcinoma cell line." (PMID 28902178, 2017). "The MET/hepatocyte growth factor (HGF) pathway is a potential candidate, since MET-induced signaling has been reported to induce PD-L1 expression in renal cell cancers." (PMID 29137273, 2017). "Recent studies have found several factors that could regulate the metastasis of renal cell carcinoma, such as VEGF, HIF-1α, HIF-2α, HGF, and E-cadherin, yet, how these factors are regulated remains unclear." (PMID 31672157, 2019). "These biomarkers were selected based on biological relevance to renal cell carcinoma, previous reports of prognostic significance, and the target profile of cabozantinib including both cabozantinib receptor targets (VEGFR2, MET, and AXL) and their ligands (VEGF, HGF, and GAS6)." (PMID 34364385, 2021). "Renal Cell Carcinoma Pathway assigned of 49/66 CNA genes RAF1 (16/26) and VHL (14/26) as G1 top-ranks with Fisher’s exact test p-values of 0.00228 and 0.0004437 (respectively) and SOS2 (7/20), HGF (4/20) and BRAF (3/20) as G3 top-ranks with p-values of 0.17, 0.51 and 0.075, respectively." (PMID 28486536, 2017). "The prognostic value of Hepatocyte growth factor (HGF) in non-clear cell renal cell carcinoma (RCC) is still unclear." (PMID 37170275, 2023). "Anti-HGF mAb (AMG-102, rilotumumab) has been developed to eliminate this effect, and AMG-102 is currently undergoing evaluation in the treatment of renal cell carcinoma (RCC), advanced solid tumours, and metastatic gastric esophagogastric adenocarcinoma." (PMID 28315228, 2017).
Alzheimer disease (26 papers, 2010 to 2026). A progressive, neurodegenerative disease characterized by loss of function and death of nerve cells in several areas of the brain leading to loss of cognitive function such as memory and language. "Higher serum and cerebrospinal fluid (CSF)-HGF concentrations have been previously associated with increased WMH burden in several cross-sectional studies in patients with Alzheimer’s disease and subjective memory complaints." (PMID 34253757, 2021). "We sought to examine the associations of the CSF HGF with Alzheimer’s disease (AD) pathology and cognitive function." (PMID 34615471, 2021). "The results displayed that HGF treatment reduced the apoptosis of the cells, and Ad-PKG II infection and 8-pCPT-cGMP treatment caused a significant increase of apoptosis of the cells, reversing the anti-apoptotic effect of HGF." (PMID 27147579, 2016). "Although increased levels of HGF have been reported in brain and cerebrospinal fluid (CSF) samples of patients with Alzheimer’s disease (AD), it is unclear whether peripheral HGF may be associated with cerebrovascular disease (CeVD) and dementia." (PMID 29410622, 2018). "Therefore, we assessed HGF in patients with either community-acquired meningitis or neurosurgery-associated meningitis, and compared the results to either patients with Alzheimer’s disease or controls with normal CSF." (PMID 26408034, 2015). "For example, clinical grade HUCMSCs play an important role in the repair of hippocampal neurons in SAMP8 mice (an accelerated aging mouse model of Alzheimer’s disease) by the secretion of core functional factor HGF." (PMID 34158112, 2021). "In line with this work, HGF decreases oxidative stress in an Alzheimer’s disease (AD) transgenic mouse model." (PMID 34179015, 2021). "This is a reasonable expectation because bryostatin is being explored as a treatment for Alzheimer’s disease and HGF is in clinical trials for spinal cord injury." (PMID 27978828, 2016). "A high level of HGF in the CSF has been reported in patients with Alzheimer’s disease, a chronic disorder characterized by progressive neuronal degeneration and deposits of amyloid plaques and neurofibrillary tangles." (PMID 26408034, 2015). "HGF has been found to be increased in CNS diseases, including MS and in prototypic neurodegenerative diseases, such as Alzheimer’s disease." (PMID 26039252, 2015). "Because it has been shown that inflammation is present in Alzheimer’s disease, we expected high HGF concentrations (ELISA), but low binding affinity to HGF receptors (HSPG, C-Met, SPR)." (PMID 26408034, 2015). "This review describes the role of HGF in hippocampal neurons, synaptic plasticity, and the memory impairment condition, Alzheimer's disease." (PMID 20305987, 2010). "Elevated HGF levels in cognitive impairment and Alzheimer’s disease likely represent compensatory vascular repair attempts, though these may be insufficient to counterbalance ongoing injury." (PMID 40718100, 2025). "The relationship between HGF and Alzheimer’s disease has been studied." (PMID 40564462, 2025). "Further, TNS3 interacts with AD-related druggable genes EGF and HGF, which in turn interact with EGFR (eFigure-11), a gene that was recently implicated in Alzheimer’s disease through GWAS15 and itself shows strong potential as a dual drug target for cancer and AD68." (PMID 41404291, 2025). "Moreover, it has been demonstrated that hUC‐MSCs alleviate neuropathological changes in Alzheimer's disease (AD) models by secreting hepatocyte growth factor (HGF), enhancing synaptic plasticity, and promoting endogenous neurogenesis." (PMID 41078306, 2025). "Interestingly, it was previously shown that HGF released from MSCs improved functional recovery in Alzheimer’s disease and multiple sclerosis models." (PMID 35109928, 2022).
Alzheimer disease (continued). "The tyrosine kinase receptor c-Met that binds hepatocyte growth factor (HGF) and that is associated with memory and learning consolidation is one candidate being implicated in Alzheimer’s disease (AD)." (PMID 33178027, 2020). "Previous studies have reported elevated concentrations of CSF-derived HGF in Alzheimer’s disease." (PMID 26408034, 2015). "It has been reported that HGF-induced Met activation exerts beneficial neuroprotective effects in preclinical models of cerebral ischaemia, spinal cord injuries and neurological pathologies, such as Alzheimer’s disease, amyotrophic lateral sclerosis and multiple sclerosis." (PMID 36344661, 2023). "One study found that HGF expression in the cerebrospinal fluid (CSF) of Alzheimer disease (AD) patients was higher than in that of patients with other neurological diseases; the AUC for the diagnosis of AD reached 0.802." (PMID 37485530, 2023). "Our observation of high binding affinity of CSF to HSPG in SPR might indicate the role of HSPG in etiology and pathophysiology of Alzheimer’s disease, not relating to presence or biological activity of HGF in CSF." (PMID 26408034, 2015). "Together, the results of these studies support the potential of positive modulators of HGF/MET to be used as novel therapeutics and suggest the drug candidate fosgonimeton might protect against neurodegeneration and be therapeutic in the management of Alzheimer’s disease and other types of dementia." (PMID 36538176, 2023).
atherosclerosis (26 papers, 2011 to 2025). A disease characterized by the build-up of fatty material and calcium deposition in the arterial wall resulting in partial or complete occlusion of the arterial lumen. "In atherosclerosis, HGF was found to be associated with disease progression, whereas in a pancreatitis model in mice and in drug-induced oxidative liver damage, results displayed protective effects of the administration of recombinant human HGF." (PMID 30538805, 2018). "Serum HGF has been linked with progression of atherosclerosis, and localised expression of HGF and its receptor, c-Met, have been detected in atherosclerotic lesions." (PMID 21920521, 2011). "In the vasculature, HGF/c-Met signalling has been associated with endothelial dysfunction and angiogenesis, and more recently with atherosclerosis." (PMID 21920521, 2011). "On the other hand, elevated circulating HGF has also been associated with greater progression of atherosclerosis in 12-year follow-up40, though it might only be a biomarker of proceeding atherosclerosis, not the cause of it." (PMID 39068298, 2024). "In accordance with our findings, the level of HGF has previously been found to be independently associated with the progression of atherosclerosis and clinical events in patients with CHD and heart failure and with long-term mortality in the general population." (PMID 33439866, 2021). "Since hypertension and endothelial dysfunction have a bidirectional relationship, circulating CD34-positive cell levels may influence the association between HGF and atherosclerosis." (PMID 29724162, 2018). "Therefore, even though HGF has a beneficial effect on vascular endothelial repair, subjects with a high plasma HGF concentration likely have a high risk of atherosclerosis (endothelial dysfunction)." (PMID 26818627, 2016). "Linked with those previous studies, a Japanese study revealed the association between HGF polymorphisms and BP or atherosclerosis and suggested that the HGF located at chromosome 7q11.2-q21 is a candidate gene for atherosclerosis." (PMID 29208002, 2017). "Beyond its regenerative role in hepatic tissue, HGF has been shown to contribute to endothelial repair and the formation of collateral blood vessels, improving perfusion in ischemic tissues affected by atherosclerosis." (PMID 40565778, 2025). "It was recently shown that HGF is associated with progression of atherosclerosis, which perhaps could reflect a compensatory and repairing function of HGF in atherosclerosis." (PMID 33781199, 2021). "It has been found that AD patients have increased levels of markers of atherosclerosis including fractalkine/CX3CL1, CCL8, M-CSF, and HGF, as well as increased levels of mediators of atherosclerosis such as E-selectin or PI3/elafin, CCL17, and IL-16, which are proportional to SCORAD." (PMID 34551806, 2021). "HGF also accelerated the progression of atherosclerosis, and melatonin inhibited macrophage infiltration and promoted plaque stabilization by upregulating the anti-inflammatory HGF/c-Met system in atherosclerotic rabbit ultrasmall superparamagnetic iron oxides (USPIO)-enhanced MRI assessment." (PMID 34421795, 2021). "Moreover, HGF is a potent inducer of angiogenesis and has a protective role in the development of cardiovascular diseases through modulation of atherosclerosis." (PMID 30083132, 2018). "Secondly, patients with HBV infection may exhibit an increase in some cytokines, such as hepatocyte growth factor, which may play a role in anti-atherosclerosis effects by protecting the vascular endothelium." (PMID 28938669, 2017). "Because HGF is overexpressed in human atherosclerotic plaques, it is necessary to conduct future study on AC2′s potential in atherosclerosis." (PMID 38111673, 2024). "Mediators involved in atherosclerosis (CX3CL1/fractalkine, CCL8, M-CSF, CXCL5, CCL4, HGF), tissue remodeling (MMP-12, MMP-1, MMP-10) and angiogenesis (VEGF-A) were also increased in AD." (PMID 28821884, 2017).